INS (insulin)
Diseases named in the same sentence as INS in open-access papers (continued):
Sharing a sentence is not in itself a finding about the gene and the disease.
Hyperinsulinemia (continued). "In the state of IR, the body compensates for resistance in skeletal muscle, adipose tissue, and liver by increasing insulin secretion, leading to hyperinsulinemia." (PMID 38378872, 2024). "Consistently, the current studies demonstrated that elevated insulin levels increase type I collagen production in HSCs, underscoring the direct profibrotic effect of hyperinsulinemia." (PMID 40808720, 2024). "When the capacity of insulin to fulfill these metabolic functions is compromised, compensatory hyperinsulinemia emerges, a phenomenon commonly referred to as insulin IR." (PMID 39771535, 2024). "We have previously shown that the animals in this model develop both reproductive and metabolic features of the syndrome, including weight gain, increased visceral adiposity, hyperinsulinemia, and decreased systemic insulin sensitivity." (PMID 39268230, 2024). "IR is characterized by decreased sensitivity of body tissues and cells to insulin, leading to compensatory insulin secretion by pancreatic β-cells and ultimately resulting in hyperinsulinemia." (PMID 38542170, 2024). "Metformin as an insulin-sensitizing drug has beneficial effects in reducing hyperinsulinemia, improving lipid profile, and increasing ovulation in patients with PCOS, but it is less effective in improving clinical hyperandrogenism and hirsutism." (PMID 38911242, 2024). "Feeding dogs a HFD leads to body weight gain, primarily driven by the expansion of adipose tissue, with accompanying fasting hyperinsulinemia and impaired insulin sensitivity." (PMID 38825593, 2024). "On the contrary, exogenous insulin is absorbed from the subcutaneous tissue to the peripheral circulation, resulting in relative peripheral hyperinsulinemia and hepatic hypoinsulinemia (i.e., low portal-to-peripheral insulin ratio)." (PMID 39906033, 2024). "As a first physiological response to IR, pancreatic β-cells orchestrate a compensatory insulin hypersecretion, thereby leading to hyperinsulinemia." (PMID 39408212, 2024). "Biochemical investigations during hypoglycemic episodes revealed elevated C-peptide and insulin levels, consistent with endogenous hyperinsulinemia." (PMID 39070407, 2024). "When fat cells fail to respond to insulin effectively, the pancreas produce more insulin as a compensatory mechanism, leading to hyperinsulinemia." (PMID 39022674, 2024). "A previous study reported an RMS patient who initially had hyperinsulinemia, but his insulin levels gradually decreased, and finally the proband died due to ketoacidosis." (PMID 38957655, 2024). "On the one hand, iron can affect the secretion and sensitivity of insulin and inhibit liver glycogen production, and insulin secretion decreases with increasing liver iron storage, leading to systemic hyperinsulinemia." (PMID 39157678, 2024). "According to a study, insulin plays a role in mediating Na+ channels, and consequently, hyperinsulinemia leads to Na+ channel dysfunction, which further remodels the vasculature." (PMID 39309107, 2024). "In this study, EVOO completely replaced the fatty acid supply in lard, and the HFD-EVOO significantly improved blood glucose levels, hyperinsulinemia, impaired glucose tolerance, and enhanced insulin sensitivity in T2D mice." (PMID 38501107, 2024). "Hyperinsulinemia can result from IR when β-cell compensatively produces more insulin to overcome IR and maintain normal blood glucose levels." (PMID 39606490, 2024). "Hyperinsulinemia ensues from a combination of genetic and environmental factors and is characterized by high fasting plasma insulin levels and an exaggerated insulin response to increased plasma glucose concentrations." (PMID 39050345, 2024). "Compensatory hyperinsulinemia, which results from decreased insulin sensitivity, works to maintain normal blood glucose levels by enhancing insulin-mediated glucose uptake in adipocytes and rhabdomyocytes." (PMID 40071249, 2024).
Hyperinsulinemia (continued). "The MKR mouse model, which experiences constant high insulin exposure, supports the link between increased hypothalamic miR-1983 and hyperinsulinemia." (PMID 39684879, 2024). "Epidemiological studies have shown that hyperinsulinemia is associated with an increased risk of PDAC and poor survival rates, while reducing insulin production can inhibit pancreatic intraepithelial neoplasia (PanIN) precancerous lesions in Kras mutant mice." (PMID 39769097, 2024). "Hyperinsulinemia has also been correlated to body condition score, with higher concentrations of insulin found in fatter horses." (PMID 38473112, 2024). "For this reason, increased circulating insulin levels (hyperinsulinemia) are necessary to maintain blood glucose within the normal range." (PMID 38672161, 2024). "This leads to hyperinsulinemia and low C-peptide levels, resulting in a dissociation phenomenon between insulin and C-peptide." (PMID 39575003, 2024). "Hyperinsulinemia was defined as fasting serum insulin levels ≥10 U/ml, while IR was measured using the HOMA-IR index (≥2.6, 66.7th percentile)." (PMID 39606490, 2024). "This study aimed to prospectively investigate the impact of insulin signaling and hyperinsulinemia on the function of CD4+ T cells in RA." (PMID 39768214, 2024). "The term hyperinsulinemia-associated laminitis (HAL) has been coined to describe some of these cases, as elevated insulin concentrations in the blood can cause acute laminitis." (PMID 38473112, 2024). "Data from both animal and human studies have established a clear link between peripheral insulin abnormalities (e.g., hyperinsulinemia, insulin resistance) and impaired neuronal function in AD." (PMID 38441832, 2024). "Hyperinsulinemia potentiates lipogenesis and FA accumulation leading to hepatotoxicity and inflammation/fibrosis, while insulin sensitivity prevents these effects by favoring the transport of fat from liver to adipose stores." (PMID 39061835, 2024). "Various drugs have been found to mitigate the stimulatory effects of hyperinsulinemia on lung cancer growth by enhancing insulin sensitivity and reducing circulating insulin levels." (PMID 38243188, 2024). "Insulin and hyperinsulinemia reduce the renal fractional excretion of UA and play a key role in the genesis of hyperuricemia and gout." (PMID 38474414, 2024). "Hyperinsulinemia and aldosterone elevate sodium channel activity in vascular cells, while cardiovascular inflammation hinders insulin signaling and diminishes nitric oxide production, promoting arterial stiffness and hypertension." (PMID 38954387, 2024). "The hormonal milieu and ROS excess drive a net increase in TG stores in the presence of hyperinsulinemia or a net decrease when basal insulin is low." (PMID 38212644, 2024). "Reduced hepatic insulin clearance has been identified as a critical factor in the pathogenesis of hyperinsulinemia in the metabolic syndrome." (PMID 38791525, 2024). "Acne is induced by hyperinsulinemia, and together with low insulin response and high protein doses, it has been deduced that these factors increase acne symptoms in child and adolescent patients." (PMID 38794680, 2024). "This article aims to alert medical professionals about diabetic patients who have hyperinsulinemia, insulin antibodies, and difficulty controlling blood sugar due to EIAS." (PMID 39575003, 2024). "Carter fed horses 200% of their energy requirements to achieve an increase of 2 body condition scores (avg BCS = 8) and reported that insulin sensitivity decreased by 71%, along with horses presenting with basal hyperinsulinemia and hyperleptinemia." (PMID 38473112, 2024). "IR is characterized by reduced insulin sensitivity, decreased cellular glucose uptake, increased insulin secretion, and exacerbated hyperinsulinemia, which further worsens hepatic IR." (PMID 39339660, 2024). "At the age of 21 days, the GK rats also presented hyperinsulinemia, with increased plasma insulin levels than the control group." (PMID 39408569, 2024).
Hyperinsulinemia (continued). "Hyperinsulinemia reflected in CSF chronically elevates insulin and renders neurons resistant to insulin." (PMID 38361318, 2024). "In contrast, mutations that increase GCK activity cause hyperinsulinism (GCK-HI), which is characterized by excessive insulin secretion." (PMID 39245718, 2024). "This technique involves the infusion of insulin to achieve a state of hyperinsulinemia, while simultaneously infusing glucose to maintain euglycemia." (PMID 39578883, 2024). "Correct glucose concentration in case of insulin resistance increases insulin secretion by pancreatic beta-cells (hyperinsulinism)." (PMID 38257363, 2024). "This increased insulin secretion is observed in response to intravenous stimulation of glucose, resulting in hyperinsulinemia." (PMID 39245718, 2024). "This consists of pursuing the possibility of exogenous insulin administration, critical illness, organ failure, and endogenous hyperinsulinism." (PMID 39077286, 2024). "Administration of estradiol and HFD led to a significant increase in insulin level (hyperinsulinemia) of PCOS animals as compared to NCG." (PMID 37483646, 2023). "A growing body of evidence suggests that insulin metabolism-related disorders such as central obesity, IR, and hyperinsulinemia can contribute to the progression and development of kidney dysfunction and an increased risk of CKD." (PMID 36624389, 2023). "We observed a significant reduction of glucose plasma levels in O with respect to N in the presence of higher plasma levels of insulin and Hb1ac, confirming a condition of hyperinsulinemia in obese subjects." (PMID 37626791, 2023). "When the body’s energy intake exceeds the energy consumed, blood glucose levels rise, insulin is secreted in large quantities, and hyperinsulinemia occurs." (PMID 37893758, 2023). "Hyperinsulinemia is a condition characterized by excessively high levels of insulin in the bloodstream." (PMID 36832286, 2023). "Enhanced insulin signaling during compensatory hyperinsulinemia increases the activity of pancreatic duodenal homeobox 1 (PDX1) which is a transcription factor that augments β-cells proliferation." (PMID 37941908, 2023). "Accurate quantitative analysis of equine insulin in blood samples is critical for assessing hyperinsulinemia in horses." (PMID 37051514, 2023). "In compensation for IR, the synthesis of insulin in β cells increases and hyperinsulinemia occurs, leading to impaired glucose disposal." (PMID 37974292, 2023). "Such a decrease in blood glucose and a decrease in hyperinsulinemia will likely benefit glucose-insulin metabolism in the long run." (PMID 36732571, 2023). "Chronic long-lasting hyperinsulinemia, typical of IR, produces damage in target organs, and one of the recognized targets of insulin is certainly the cardiovascular system." (PMID 38001929, 2023). "It has been reported that impaired insulin clearance is a major determinant of hyperinsulinemia, and therefore, it is led to an increase in fasting and 2hpp blood glucose." (PMID 36919265, 2023). "As the blood insulin concentration increases, the brain and CSF insulin concentrations also increase correspondingly, but in a prolonged hyperinsulinemia state, insulin receptor of the BBB downregulates and insulin transport into the brain reduces." (PMID 36834911, 2023). "Hyperinsulinemia can promote the cancer cell proliferation, chemo-resistance and metastasis through stimulating insulin and insulin-like growth factor-1 receptors." (PMID 36845740, 2023). "The failure of insulin-sensitive tissues to respond appropriately to insulin leads to compensatory hyperinsulinemia, which facilitates β-cell dysfunction and death through exhaustion." (PMID 36899932, 2023). "IR is a state in which insulin is ineffective in peripheral tissues, leading to hyperinsulinemia and impaired lipid and glucose homeostasis." (PMID 37258550, 2023).
Hyperinsulinemia (continued). "The role of insulin in mediating normal growth in healthy individuals and promoting adiposity during hyperinsulinemia through maintenance of the insulin–growth hormone (GH)–insulin-like growth factor 1 (IGF-1) axis is well recognized." (PMID 37246587, 2023). "Several studies reported that hyperinsulinemia exists in T2D because the peripheral tissues lack their insulin sensitizing properties." (PMID 36672202, 2023). "Mechanistically, chronic hyperinsulinemia resulting from decreased responsiveness to insulin promotes excessive synthesis and release of leptin from adipose tissue." (PMID 38260166, 2023). "Fetal hyperinsulinemia can lead to overgrowth of insulin-sensitive tissues such as the liver, adipose tissue, and heart." (PMID 37626162, 2023). "Current evidence indicates that insulin and hyperinsulinemia promote the synthesis and biological activity of IGF-1 and IGF-2, which regulates the energy-dependent growth process." (PMID 37361533, 2023). "Portal hypertension is another suspected culprit in developing hyperinsulinemia in cirrhosis, as portosystemic shunts were found to decrease hepatic insulin extraction." (PMID 37078380, 2023). "Exposure to BPA during adulthood decreases insulin sensitivity in most cases and produces hyperinsulinemia or hypoinsulinemia depending on the timing of exposure." (PMID 37134142, 2023). "Chitosan nanoparticles have opened up a new possibility of oral insulin delivery to overcome drawbacks like needle phobia, and peripheral hyperinsulinemia." (PMID 38027185, 2023). "Measuring baseline insulin concentration as an assessment for ID has poor sensitivity, but excellent specificity, compared with performing dynamic assessment of hyperinsulinemia after oral carbohydrate challenge." (PMID 37148171, 2023). "Normal glucose tolerance is sustained in the early stages by compensatory hyperinsulinemia, eventually leading to desensitization of the peripheral tissues to insulin." (PMID 37175603, 2023). "GPR120 agonists can improve glucose tolerance, reduce hyperinsulinemia and increase insulin sensitivity of insulin in obese mice fed high-fat diets." (PMID 37196107, 2023). "Subcutaneous injections of supraphysiologic doses of insulin used in the routine treatment of patients with T1D will result in exogenous systemic hyperinsulinemia." (PMID 37957681, 2023). "Plasma insulin measurements confirmed hyperinsulinemia in Irs2–/–;Cdk4-R24C/R24C males, suggesting rescue of insulin secretory capacity in the context of at least some residual insulin resistance." (PMID 37712417, 2023). "Although, once again, insulin is life essential, too much drives hyperinsulinemia, preventing well-regulated apoptosis." (PMID 37760052, 2023). "Changes in hyperinsulinemia in response to metformin are generally interpreted as a consequence of changes in insulin sensitivity." (PMID 37623862, 2023). "In the RISC study, preexposure to hyperinsulinemia stimulated a greater insulin-induced secretory response independently of insulin sensitivity." (PMID 37200851, 2023). "At the initial stage, the β cells of the pancreas secrete elevated levels of insulin, consequently leading to hyperinsulinemia, but glucose is still transported to the cells." (PMID 37628596, 2023). "The “carbohydrate-insulin model” has been proposed, arguing that a high intake of carbohydrates leads to endocrine dysregulation marked by hyperinsulinemia, driving energy allocation and increased energy storage in adipose tissue." (PMID 37020811, 2023). "We report here that increase of REG3A, both as a transgene and as a recombinant protein, controls elevated basal insulin levels during aging, high-fat feeding, and in obese ob/ob mice and prevents glucose-induced hyperinsulinemia." (PMID 36918710, 2023). "Hyperinsulinemia is diagnosed when plasma insulin levels are greater than 2 μU/mL and the serum glucose concentration is less than 60 mg/dL." (PMID 37510690, 2023).
Hyperinsulinemia (continued). "Prolonged hyperinsulinemia is known to downregulate insulin receptors, resulting in impaired insulin transport into brain tissues and contributing to learning and memory deficits, possibly through neuroglial energy crises." (PMID 38107512, 2023). "It has also been found that during hyperinsulinemia, insulin is able to cross the blood-brain barrier and stimulate central nerves to exert sympathetic excitation." (PMID 37583585, 2023). "Delayed hyperinsulinemia was characterized by lower arsenic, chromium, cobalt, and lead metalloproteins compared to subjects with early and middle insulin peaks." (PMID 37242230, 2023). "According to reports, canagliflozin enhances B‐cell activity by lowering insulin demand and hyperinsulinemia, which are major contributors to the rise in testosterone levels in PCOS." (PMID 37985173, 2023). "Most horses with insulin dysregulation have tissue insulin resistance with compensatory hyperinsulinemia and a broad range of serum insulin concentrations." (PMID 37051514, 2023). "For this reason, increased levels of insulin are essential to achieve normal glucose tolerance, and hyperinsulinemia is one of the main features of IR states." (PMID 37298967, 2023). "We demonstrated that the increased phosphorylation in IRS1Y608 following hyperinsulinemia and acute insulin stimulation occurs in the setting of reduced activity of its tyrosine phosphatase, SHP2." (PMID 37834116, 2023). "At 30 days, OGTT in the insulin group was significantly increased (p < 0.001) in fasting (25.8%), at 60 min (65.2%) and 90 min (30.4%), with hyperinsulinemia at 60 and 90 min, 66% and 144.6% (p < 0.0001)." (PMID 37110230, 2023). "In 2000, Morin-Papunen studied the contributions of body mass, body fat distribution, and family history of T2D to hyperinsulinemia, insulin secretion, and resistance in PCOS." (PMID 36834549, 2023). "β-hydroxybutyrate production is inversely dependent on insulin levels, as hyperinsulinemia inhibits the rate of ketogenesis, and ketone bodies are cleared through their increased metabolism." (PMID 36829437, 2023). "Hyperandrogenism and anovulation are related to insulin sensitivity, compensatory hyperinsulinemia, and a rise in the ovarian androgenic response to circulating insulin." (PMID 36751233, 2023). "In contrast, treatment with Rimo-NPs affected only insulin sensitivity, reflected by the reduced glucose levels, following a bolus of insulin, reduced hyperinsulinemia, and improved HOMA-IR and ISI levels." (PMID 36442615, 2023). "Control of active acromegaly reduces hyperinsulinemia, improves insulin sensitivity, increases fat mass and glucose homeostasis in most, but not in all, studies." (PMID 36901984, 2023). "In an attempt to counteract hyperglycaemia, increased insulin production results in hyperinsulinemia." (PMID 38069300, 2023). "Hyperinsulinemia occurs when the fasting concentration of insulin in the blood remains higher than normal levels for prolonged periods." (PMID 37446104, 2023). "The second mechanism is the consequence of hyperinsulinemia due to increased BMI, which stimulates the normal growth function of insulin as well as prolonging the duration of the action of insulin-like growth factor-1 (IGF-1)." (PMID 36672434, 2023). "A major drawback of SC insulin delivery is the need for meal announcement and the peripheral hyperinsulinemia that, over time, contributes to macrovascular complications." (PMID 37229215, 2023). "This seemingly futile cycle of insulin from the pancreas to the liver is key to prevent the adverse metabolic effects of chronic hyperinsulinemia." (PMID 37834412, 2023). "The success of some interventions aimed at correcting maternal hyperinsulinemia during obese pregnancies in reducing cardiac remodelling in mouse offspring (discussed in §5) suggests that glucose/ insulin signalling is key for cardiac development." (PMID 37482780, 2023).